CTLA4 (cytotoxic T-lymphocyte associated protein 4)
Diseases named in the same sentence as CTLA4 in open-access papers (continued):
Sharing a sentence is not in itself a finding about the gene and the disease.
tumor (continued). "Treg cells are recruited into the tumor environment and inhibit NK-cell responses through CTLA-4." (PMID 35456019, 2022). "Mice survival, tumor growth, and CTLA-4/Foxp3 expression in peripheral blood cells were measured." (PMID 36015348, 2022). "The use of a monotherapy against either PD-1/PD-L1 or CTLA-4/CD80 may apply a positive selection pressure to a tumor, resulting in the outgrowth of clones that are able to modulate other immune checkpoints." (PMID 36497220, 2022). "In tumors, CTLA-4 and PD-1/PD-L1 can favor tumor evasion from immune surveillance, so that their inhibition can produce an increased immune activation and overcome the typical tumor-induced immunosuppression." (PMID 36612243, 2022). "Various immune checkpoints are the mature targets in tumor immunotherapy, like PD1/PD-L1 (Programmed Cell Death 1/ Programmed Cell Death Ligand 1), CTLA4 (Cytotoxic T-Lymphocyte Associated Protein 4) and LAG3 (Lymphocyte Activating 3), are in ongoing clinical trials." (PMID 35831836, 2022). "To explore whether combination with anti-CTLA-4 could enhance the antitumor efficacy of YST-OVH, we performed i.t. injection of YST-OVH with intraperitoneal (i.p.)injection of anti-CTLA-4 to treat the Hepa1-6 bilateral flank tumor model." (PMID 35688558, 2022). "At the endpoint of tumor inhibition experiment, the tumor weight of nanovaccine group and anti-CTLA-4 mAb group was significantly lower than that of PBS group, and the tumor weight of the combo group was significantly lower than that of each single treatment group." (PMID 34875483, 2022). "ICB therapy using a combination of PD-L1 and CTLA-4 blocking antibodies has been shown to reverse tumor-specific effector T cell exhaustion and increase the number of tumor-infiltrating lymphocytes (TILs) present, resulting in improved anti-tumor immune responses." (PMID 35154092, 2022). "The oral administration of various Bacteroides alone or in combination with Burkholderia cepacia restored the tumor-suppressing effects of CTLA-4 blockade by augmenting Th1 responses in tumor-draining lymph nodes and promoting intratumoral dendritic cells maturation." (PMID 36142843, 2022). "In support of our findings, a similar observation of the improved anti-tumor effect has been documented with the combination of IDO-targeting Salmonella and PD-1/CTLA-4 inhibitors in the murine LLC1 tumor model in comparison to either Salmonella alone or PD-1/CTL1-4 mAb alone." (PMID 36605208, 2022). "One study showed that in GBM-bearing mice, depleting MDSCs using the antibody against Gr1, an immune marker for mouse MDSCs, strongly enhanced the efficacy of tumor-targeted gene therapy, and when combined with anti-PD-L1 or CTLA-4 treatment, greatly improved overall animal survival." (PMID 35920986, 2022). "Additionally, tumor cells can also evade immune responses and immunotherapy by utilizing immune checkpoint genes, such as PD-1, PD-L1, and CTLA-4." (PMID 35874816, 2022). "Altogether, this preclinical work suggested that the anti-tumor immune responses induced by CTLA-4 and PD-1 blockade may represent relevant therapeutic and potentially synergistic strategies, repressing tumor progression dependent of cancer indication." (PMID 35339889, 2022). "Consequently, the ICI targeting CTLA-4 aims to reinvigorate T-cell activation to counteract the ability of tumour cells to escape immunosurveillance." (PMID 35326677, 2022). "There was an increased expression of CTLA4 in the tumor group compared with normal tissue." (PMID 35872842, 2022). "However, it can also be explained that CTLA-4, an important immunosuppressive molecule, can be used by tumor cells to induce immunosuppressive state and make tumor growth and development." (PMID 36211357, 2022). "CTLA-4 was confirmed to be another immune checkpoint molecule that mediates tumor immune tolerance." (PMID 36230955, 2022).
tumor (continued). "Moreover, the immune checkpoint molecules PD-1 and CTLA4, when combined with the corresponding ligands, inhibit the killing effect of T cells on the tumor and the activation of T cells." (PMID 35401561, 2022). "Ipilimumab is the first cytotoxic T lymphocyte-associated protein 4 (CTLA-4) immune checkpoint inhibitor that increases T cell activation and proliferation by blocking CTLA-4 binding to its ligand (CD80/CD86) and participates in the tumor immune response." (PMID 35368898, 2022). "Immune checkpoints, represented by cytotoxic T lymphocyte antigen 4 (CTLA-4) and programmed cell death protein 1 (PD-1) and its ligand 1 (PD-L1), are the most studied targets of immune escape through the negative regulation of T lymphocytes by tumor cells." (PMID 35330068, 2022). "Therefore, we mixed MC38-B7x and MC38-Control cells at a 1:1 ratio, engrafted this mixed tumor into mice, and then treated mice with either anti-CTLA-4 or isotype antibody." (PMID 35523809, 2022). "CTLA-4 is often overexpressed in a chronic inflammatory status, such as in cancer, implying that its presence in the tumor microenvironment may be involved in the dysregulation of the immune response." (PMID 35330479, 2022). "In a more indirect manner, CTLA-4 targeting could deplete regulatory T-cells within the tumor site in a non-small cell lung cancer in vivo model, by that increasing the cytotoxic functionality of tumor-resident NK cells." (PMID 34374809, 2022). "Despite the fact that previous studies demonstrated that tumors harboring BRCA1/2 dysfunction and treated with PARPi could increase tumor immunogenicity, therefore sensitizing tumor cells to anti-CTLA4 agents, the whole process remains understudied." (PMID 36533080, 2022). "Given that anti CTLA-4 has previously been shown to be highly effective against AB12 tumors we selected using this agent to test whether AB12 tumor respond to immunotherapy in a tumor growth phase dependent manner." (PMID 36685577, 2022). "In contrast, CTLA-4 staining was prominent in all tumor samples investigated." (PMID 35628262, 2022). "Though anti-CTLA-4 and anti-PD-1/PD-L1 are the most clinically utilized immune checkpoint antibodies, there has been robust investigation into the effectiveness of other immune checkpoint targeting antibodies to stimulate an anti-tumour immune response." (PMID 35402250, 2022). "However, the expression pattern, correlation with tumor-infiltrating lymphocytes, and prognostic value of CTLA-4 and CD86 in RC after nCRT/nCT are yet to be further elucidated." (PMID 36428666, 2022). "However, compared with the anti-CTLA-4 antibody, more aptamer was required to elicit inhibition of tumor growth in vivo." (PMID 36015348, 2022). "Combination blockade of CD47 and PD1, CTLA4 also achieved better anti-tumor effect." (PMID 35697717, 2022). "Whether CTLA4 also depletes Teff CD80, and whether Teff CD80 and Treg CTLA4 regulate Teff reinvigoration or migration, and hence tumor regression, need further investigation." (PMID 35449134, 2022). "Combining anti-CTLA-4 with radiation led to partial responses in the primary tumor." (PMID 36275767, 2022). "Higher tumor TIDE prediction scores were associated not only with poor immune checkpoint suppression therapy but also with poor patient survival under anti-PD1 and anti-CTLA4 therapy." (PMID 36338978, 2022). "Moreover, CD8 and CD4 depletion inhibits the anti-CTLA-4 effect in CT26 subcutaneous models suggesting a primordial role of T cell modulation in the tumor microenvironment as a mechanism of action behind the anti-cancer efficacy of anti-CTLA-4." (PMID 35339889, 2022). "Furthermore, immune checkpoint receptors such as programmed cell death receptor 1 (PD-1) and cytotoxic T lymphocyte antigen 4 (CTLA-4) are found to be upregulated in tumor progression." (PMID 35154149, 2022). "Consequently, targeted therapies against CTLA-4 or PD-1/PD-L1 signaling pathways can rejuvenate the anti-tumor response and generate a good clinical response." (PMID 36247496, 2022).
tumor (continued). "The combination of PIC + RT + anti-CTLA-4 in this tumor model rendered 62.5% (5/8) of mice disease-free, vs. only 37.5% (3/8) of mice treated with RT + anti-CTLA-4; this was associated with a significant improvement in tumor growth inhibition and overall mice survival." (PMID 35999216, 2022). "In support of this hypothesis, cancer patients given anti-CTLA-4 and anti-PD-1 therapy develop tumor-specific cytolytic CD4 T cells marked by enhanced Eomes expression." (PMID 36358898, 2022). "CTLA-4 or PD1 blockade unleashes cytotoxic T cell activity against the tumor." (PMID 35585623, 2022). "ICB are molecules that restore the immune system’s ability to recognize and eliminate tumor cells such as PD1/PDL1 (program cell-death protein one and its ligand) or CTLA4 (cytotoxic T-lymphocyte associated protein 4) inhibitors have revolutionized the treatment of some adult cancers." (PMID 36304921, 2022). "Tumor cells, on the other hand, may regularly control immunological checkpoints like programmed death-1 (PD-1) and cytotoxic T-lymphocyte antigen-4 (CTLA-4), which are overexpressed on T cells." (PMID 35392957, 2022). "These infiltrates and tumor cells contribute to the production of tumor-supporting growth factors, chemokines, and cytokines, and the antitumor immunity declines because of immune checkpoint proteins such as CTLA-4 or PD-1." (PMID 35814023, 2022). "The expression of PD-1 in tumor-infiltrating lymphocytes and PD-L1/CTLA4 in the tumor cell membrane may be predictive for the response to immune checkpoint therapies." (PMID 36275809, 2022). "Interestingly, we found that B7x reduced the expression of cell-surface CTLA-4 on tumor-infiltrating Tregs in vivo and induced Tregs in vitro." (PMID 35523809, 2022). "Recently, a study showed that inhibition of tumor glycolysis contributes to the therapeutic effect of CTLA-4 blockade, and the combination of CTLA-4 blockade and tumor glycolysis inhibitors may be considered." (PMID 36387147, 2022). "Monotherapy with YST-OVH or anti-CTLA-4 significantly inhibited the tumor growth in both flanks." (PMID 35688558, 2022). "In particular, TIM-3 and LAG-3 were upregulated on tumour-infiltrating T cells and may represent novel targets in combination with PD-1 and/or CTLA-4 ICBs." (PMID 35366537, 2022). "With the development of tumor behaviors and immunological molecular mechanisms, immunotherapy provides a novel site for tumor targeting therapy, especially immune checkpoint inhibitors (ICIs), including CTLA4, PD-1, and PD-L1." (PMID 36248908, 2022). "Early studies proved that the administration of antibodies against CTLA-4 results not only in tumor shrinkage but may also protect against tumor relapse." (PMID 36613706, 2022). "Therefore, the anti-CTLA-4 antibody therapy can be carried out at the same time of radiotherapy to achieve better anti-tumor immune effect." (PMID 35371055, 2022). "In this report, we employ live and ex vivo imaging to examine whether peri-tumor administration specifically targets anti-CTLA-4 to tumor-draining lymph nodes (TDLN) and whether the incorporation of hyaluronidase enhances this effect." (PMID 35621582, 2022). "The combination of Lactobacillus acidophilus lysate and anti-CTLA-4 therapy could enhance anti-tumour immunity in a mouse model of colon cancer, accompanied with increased CD8 + T cells and effector memory T cells, but decreased Treg cells and M2 macrophages." (PMID 36569832, 2022). "In addition, some patients receiving anti-CTLA-4 monoclonal Ab (mAb) and anti-PD-1 mAb have shown resistance to ICIs to varying degrees due to tumor-extrinsic and/or -intrinsic factors." (PMID 35669786, 2022). "In addition, using cytometry-based multiplex analysis, we showed that anti-CTLA-4 and anti-PD-1 affected the tumor immune microenvironment differently and in particular the tumor immune infiltration." (PMID 35339889, 2022).
tumor (continued). "Negative regulators of the immune response cytotoxic T-lymphocyte associated protein-4 (CTLA-4) and the programed death receptor 1 (PD-1), as well as its ligands, programmed death ligands 1 and 2 (PD-L1 and PD-L2), became main targets of tumor immunotherapies." (PMID 36613518, 2022). "ICOS molecules are abundantly expressed in the mouse model tumor treated with anti-CTLA-4, suggesting that ICOS may improve the efficacy of immunotherapy." (PMID 35909469, 2022). "This anti-CTLA-4 dosing range (50 to 100 μg) is based on earlier studies with the same tumor model." (PMID 35890247, 2022). "In addition, 8 Gy*3f was more effective than 6 Gy*5f in eliciting systemic anti-tumor immunity combined with anti-CTLA-4 antibody." (PMID 36713375, 2022). "However, the most potent mechanism to limit normal anti-tumor immune responses is the activation of immune checkpoint pathways such as cytotoxic T-lymphocyte antigen 4 (CTLA-4), programmed death 1 (PD-1) and programmed death ligand-1 (PD-L1)." (PMID 36551630, 2022). "The representative drugs include monoclonal antibodies against programmed cell death receptor-1 (PD-1), cytotoxic T-lymphocyte-associated antigen 4 (CTLA-4), and lymphocyte-activation gene 3 (LAG3), which inhibit T cell activity and contribute to immune evasion from the tumor." (PMID 35596181, 2022). "In both genetic and syngeneic mice models of PDAC, combination of the FAK inhibitor VS-4718 with the chemotherapeutic agent gemcitabine and anti-PD-1 and/or anti-CTLA-4 therapy achieved a maximal response in terms of reducing tumor progression and increasing survival." (PMID 35053602, 2022). "Also, treatment with anti-CTLA-4 antibodies has shown promising anti-tumor effects in MC38 and CT26 tumor adenocarcinoma tumor models induced by selective attenuation of intra-tumor Treg with active T cell activation." (PMID 35392976, 2022). "CTLA-4 conditional knockout (KO) in Treg cells reduces tumor growth." (PMID 35164813, 2022). "A DCs-based vaccine combined with CTLA-4 inhibitor enhanced anti-tumor response." (PMID 36246629, 2022). "Understanding the Treg/Th17 axis in tumor development may provide an opportunity to either enhance or abrogate Th17 functions in Tregs to improve the efficacy and side effects of anti-CTLA-4." (PMID 35326731, 2022). "Additionally, intra-tumoral depletion of Tregs in CT26 colon carcinoma tumor-bearing mice was positively correlated with CD107a expression on intra-tumoral NK cells after anti-CTLA-4 treatment." (PMID 35326731, 2022). "The administration of tandem peptide nanocomplex (TPNC) carrying CpG DNA ligand of TLR9s (iTPNC) can suppress tumor growth in several animal models of various cancers, resulting in an abscopal effect on distant tumors, and improving responsiveness to anti-CTLA-4 treatment." (PMID 36338731, 2022). "Anti-PD-1 and anti-CTLA4 can re-activate the anti-tumor response, leading to tumor regression." (PMID 36276141, 2022). "Since CTLA-4 inhibits T cell activity in secondary lymphatic organs and PD-1/PD-L1 regulates T cell function in malignant tissues and the tumor microenvironment, PD-1/PD-L1 inhibitors due to the specificity of the PD-1/PD-L1 signaling pathway lead to minimal damage to healthy tissue." (PMID 36276117, 2022). "Consistent with the B16.BL6 tumor–bearing mouse findings, neutrophil depletion in LLC1 tumor–bearing mice treated with dual CTLA-4 and PD-1 blockade resulted in LLC1 tumors growing more slowly in mice receiving vehicle treatment and more rapidly in mice receiving 7HP349." (PMID 35552271, 2022). "Interestingly, we found higher expression of Ctla4 and Lag3 in Myc-R26Met compared with Alb-R26Met tumours." (PMID 36433941, 2022). "Mice treated with the combination of AHCC® and DICB had increased expression of the cytotoxic molecule granzyme B, the cell proliferation marker Ki-67, and the cell activation marker CTLA-4 by tumor infiltrating CD8+ T cells compared to mice treated with water and DICB." (PMID 35514996, 2022).
tumor (continued). "Some in vitro studies demonstrated that co-inhibitory molecules programmed cell death protein 1 (PD-1) and cytotoxic T lymphocyte-associated protein 4 (CTLA-4) could attenuate glycolysis in CD8+ T cells and suppress their anti-tumor function." (PMID 35864520, 2022). "Indeed, anti-PD-1/anti-CTLA-4 treatment of Keap1f/f/Ptenf/f spontaneous lung tumors resulted in tumor regression." (PMID 36439878, 2022). "Immune checkpoint blockades (ICBs), including antibodies to PD-1, PD-L1 or CTLA-4, etc, may be effective in treating BCa, nevertheless, their response rates remain relatively low in unselected tumor patients." (PMID 36300085, 2022). "Significantly increased tumour inhibition was observed in mice receiving the combination treatment of antibodies, compared with mice receiving monotherapy of the specific antibodies (CTLA-4 p = 0.0207, interleukin-6 p = 0.0002)." (PMID 35626020, 2022). "Accordingly, the anti-CTLA4 antibody can be usually considered as a common ICB agent for improved PDIT, which can inhibit tumor immune escape by effectively blocking CTLA4 on the surface of T cells, further activating a large number of CD8+ T cells to eliminate tumors." (PMID 35910806, 2022). "Our risk score model positively correlated with CTLA-4 (R = 0.33), which may be associated with CTLA-4 blocking and increased number of IFN-γ -producing tumor-infiltrating T-cell." (PMID 36712869, 2022). "However, the anti-CTLA4 antibody combined with the cabozantinib plus chidamide-k30 regimen was more effective for inhibiting tumor growth than the anti-PD-L1 or anti-PD-1 antibody combination regimens." (PMID 36142591, 2022). "TMV-based vaccine-mediated immunotherapy combined with anti-cytotoxic T-lymphocyte-associated protein 4 monoclonal antibody (anti-CTLA-4 mAb) treatment effectively stimulated the immune system, enhanced the immunity of CD8+ T cells, reduced tumor metastasis and improved the survival rate." (PMID 35524277, 2022). "We then asked whether tumor-targeted desialylation could be combined with PD-1 and CTLA-4 blockade in the B16D5-HER2 model." (PMID 36322632, 2022). "Moreover, RNA levels of PD1 and CTLA4 were low in DCZ0415‐treated tumours as compared to tumours of mice treated with vehicle." (PMID 35194944, 2022). "Among these immune-associated ligands and receptors, CTLA4, CCR5 and CSF1R could contribute to tumor immune suppression, while TNFRSF1B and type II IFNR are associated with stimulation in neutrophils." (PMID 36443332, 2022). "Furthermore, the treatment with AS1411-SMG1 AsiCs sensitizes the tumor to ICB therapy with anti-CTLA-4/PD-1 antibodies." (PMID 35991316, 2022). "In addition to CTLA-4, PD-1 is another common immunosuppressive molecule on the surface of T-cells, which are expressed on the surface of various tumor cells." (PMID 36618938, 2022). "In addition to immunotherapy targeting PD-1, Cytotoxic T-lymphocyte antigen 4(CTLA-4) is also a common target for tumor immunotherapy." (PMID 35590394, 2022). "Besides, direct measles virus and oHSV expressing IL-12 plus PD-1 and CTLA-4 blockade therapy stimulated tumor regression mainly by inducing the Th1, CTL cells, and M1-macrophages activation in the glioma murine model." (PMID 34980128, 2022). "Indeed, in ICI-resistant murine models, the combination of anti-CTLA-4 or anti-PD-1 mAbs with IPI-549 significantly delayed tumor growth in comparison to ICI monotherapies." (PMID 35345849, 2022). "Ipilimumab, an inhibitor of CTLA-4, may promote T-cell activation and subsequent anti-tumor immunity." (PMID 36291069, 2022). "Immune checkpoint inhibitor therapies (ICIs) targeting immune checkpoints such as cytotoxic T-lymphocyte-associated antigen 4 (CTLA-4), programmed cell death protein (PD-1), and its ligand (PD-L1) have produced long-term tumor responses in multiple advanced cancers." (PMID 35565405, 2022). "Moreover, the expression of the checkpoint molecules PD-1, PD-L1 and CTLA-4 on T cells, macrophages and tumor cells was also investigated." (PMID 36123711, 2022).